Y_RNA (Y RNA )
Gene: Miscellaneous RNA gene on chromosome 15 (50,221,888 to 50,221,996, forward strand). Ensembl gene ENSG00000200605.
Homologues: Orthologues: chimpanzee Y_RNA (100% identical), macaque Y_RNA (97% identical), guinea pig Y_RNA (91% identical), guinea pig Y_RNA (90% identical), guinea pig Y_RNA (88% identical), guinea pig Y_RNA (86% identical). Paralogues in human: RNY1 (93% identical), Y_RNA (91% identical), Y_RNA (90% identical), Y_RNA (89% identical), Y_RNA (88% identical), Y_RNA (87% identical), RNY1P7 (86% identical), Y_RNA (86% identical), RNY1P11 (85% identical), RNY1P8 (85% identical), Y_RNA (85% identical), Y_RNA (84% identical), and 99 more.